CRKL (CRK like proto-oncogene, adaptor protein)
Diseases named in the same sentence as CRKL in open-access papers (continued):
Sharing a sentence is not in itself a finding about the gene and the disease.
cervical cancer (continued). "We analyzed the expression level of CRKL in 305 cervical cancer tissue samples and 3 normal samples by referring to the RNA-seq data available from TCGA database and found a significant increased expression in cervical tumor, especially in Stage I cancer samples." (PMID 31133010, 2019). "Furthermore, we reported that more than a half of the qPCR-validated CRKL-regulated ASEs detected in HeLa cells were also correlated with the CRKL expression level in cervical cancers." (PMID 31133010, 2019). "We compared the CRKL-dependence of these 27 ASE detected both in clinical samples and HeLa cells, showing that 14 of them responded to CRKL expression levels in cervical cancer in the same direction as in HeLa cells and only 5 of them showing an apparently opposite response." (PMID 31133010, 2019). "In light of previous study and the CRKL-regulated functional pathway in mitotic cell cycle, we predicted that CRKL might regulate the proliferation of the major cell types in cervical cancer." (PMID 31133010, 2019). "In this study, we analyzed the expression level of CRKL in 305 cervical cancer tissue samples available in TCGA database, showing a significant increased expression in Stage I cancer samples (Stage I, the carcinoma is strictly confined to the cervix without invasion)." (PMID 31133010, 2019). "In the present study, we performed experiments to identify what role CRKL plays in cervical carcinoma and explore whether CRKL could regulate alternative splicing." (PMID 31133010, 2019). "In cervical cancer cell lines, ZEB1 and CrkL expression levels were found to be inversely correlated to the levels of miR-429." (PMID 40362257, 2025). "In cervical cancer, miR-429 played a role in reducing colony formation via the ZEB1 and CrkL signaling pathways." (PMID 40362257, 2025). "CRKL depletion significantly alters the retention of variable introns of PTK2B and TSC2, and the inclusion of variable exons of MELK, and these tumorigenesis involving genes might then affect development or progression of cervical carcinoma." (PMID 31133010, 2019). "CrkL overexpression also promoted cell proliferation in non-small cell lung cancer (NSCLC), cervical carcinoma, and Ishikawa endometrial carcinoma cell lines." (PMID 33801580, 2021).
pancreatic cancer (9 papers, 2015 to 2024). "Increased E-cadherin expression and decreased ZEB1 expression were observed by knockout of Crk, CrkL, or both in colon cancer cells and by Crk/CrkL double in pancreatic cancer cells." (PMID 33801580, 2021). "Lastly we report a newly identified CRKL amplification in one of our patients with metastatic pancreatic cancer." (PMID 25897431, 2015). "Crk/CrkL double knockout also inhibited pancreatic cancer cell migration and invasion." (PMID 33801580, 2021). "We identified CRKL amplification in one of our patients with advanced pancreatic cancer." (PMID 25897431, 2015). "We also screened CRKL amplifications in the FoundationOneTM pancreatic cancer database." (PMID 25897431, 2015). "In the Catalogue of Somatic Mutations in Cancer (COSMIC) database; 135/13,389 (1.0%) samples showed co-amplification of BCL2L13, BID, CRKL and MAPK1 and frequencies > 2% were found in ovarian or pancreatic carcinomas." (PMID 37443114, 2023). "The substantial decrease in the phospho-p130Cas level with Crk/CrkL double knockdown in GBM cells is consistent with our previous studies with fibroblasts and colorectal and pancreatic cancer cell lines." (PMID 33561443, 2021). "A previous study demonstrated that high expression of CRKL promoted proliferation and invasion of pancreatic cancer cells, but did not look into the clinicopathological association or prognostic values of this marker." (PMID 28558797, 2017). "In our N of 1 experience, dasatinib failed to help a patient with CRKL amplified pancreatic cancer." (PMID 25897431, 2015).
leukemia (8 papers, 2009 to 2024). A malignant (clonal) hematologic disorder, involving hematopoietic stem cells and characterized by the presence of primitive or atypical myeloid or lymphoid cells in the bone marrow and the blood. "CRKL is tightly linked to leukemia via its binding partners BCR-ABL and TEL-ABL, upregulated in multiple types of human cancers, and induce cancer cell proliferation and invasion." (PMID 31133010, 2019). "CRKL is tightly linked to leukemia via its binding partners BCR-ABL and TEL-ABL." (PMID 31133010, 2019). "Our results indicated that CRKL acted as a erythroid differentiation inhibitor in CML by promoting the aggressiveness of leukaemia cells." (PMID 38683131, 2024). "CRKL is a substrate protein for ABL, and the Tel‐ABL fusion protein can form complexes with CRKL in leukaemia, we have also shown that ETV6 directly binds to CRKL by Co‐IP assay further indicated the direct interaction between ETV6 and CRKL." (PMID 38683131, 2024). "CRKL is a substrate protein for ABL, and the Tel-ABL fusion protein can form complexes with CRKL in leukemia." (PMID 32326970, 2020). "CRKL is a 39 kDa adaptor protein and important mediator of the oncogenic effects of BCR-ABL in leukemia cells that is also expressed in endothelial cells." (PMID 37983208, 2023). "These kinases are downstream targets of functional pre‐BCR (B‐cell receptor), a distinctive feature of human TCF3‐PBX1 leukemia, and two of its main targets after pre‐BCR stimulation are CrkL and PLCg2." (PMID 33890726, 2021). "The effect of CRKL on leukaemia cell differentiation has not been reported, in our study we investigated the potential role of CRKL in erythroid differentiation of K562 cells." (PMID 38683131, 2024). "CRKL is a substrate of BCR-ABL and plays an important role in leukemia." (PMID 26274927, 2015).
colorectal cancer (7 papers, 2021 to 2025). A primary or metastatic malignant neoplasm that affects the colon or rectum. "Moreover, the increased invasion of SASH1-deficient colorectal cancer cells was completely counteracted by the removal of CrkL." (PMID 40362257, 2025). "A significant reduction in cell proliferation, chemoresistance, as well as cells forming dense and three-dimensional clusters were observed in colorectal cancer cells deficient in Crk and CrkL, and the results correlated with decreased levels of ERK1/2 phosphorylation and c-Myc protein." (PMID 40362257, 2025). "SASH1, which contains a Src-homology 3 domain, inhibited EMT by engaging with the oncoprotein CrkL in colorectal cancer cells." (PMID 40362257, 2025). "Published results indicate that PPP2R5E, PES1, RRM2B, GLRX, and CRKL are important in the prognosis and development of colorectal cancer." (PMID 37895091, 2023). "Lung, gastric, and colorectal cancer patients showed increased protein levels for both Crk and CrkL and lower survival." (PMID 33801580, 2021). "Furthermore, HAPI analysis identified potentially novel oncogenes that hijack enhancers in trans, such as CRKL in the colorectal cancer cell line HT29 and FOXJ2 in the small cell lung cancer cell line NCIH2171." (PMID 39033128, 2024). "For instance, ZEB2-AS1 could enhance epithelial-mesenchymal transition through the miR-1205/CRKL pathway in colorectal cancer and may be involved in the occurrence and development of colon cancer by regulating the glycolysis process through the miR-188/TAB3 pathway." (PMID 36420274, 2022). "Elevated expression of CrkL in cancer tissues also has been shown to lead to poor prognosis and lower survival of patients with NSCLC, ovarian cancer, gastric, pancreatic ductal adenocarcinoma, and colorectal cancer." (PMID 33801580, 2021). "In general, ALK activates multiple signaling pathways, such as the PI3K-AKT, CRKL-C3G, MEKK2/3-MEK5-ERK5, JAK-STAT and MAPK signaling pathways 19, which involved in the initiation and progression of many different cancer types, including lymphomas, neuroblastoma and colorectal cancer." (PMID 33391411, 2021).
melanoma (7 papers, 2020 to 2024). A malignant, usually aggressive tumor composed of atypical, neoplastic melanocytes. "successfully created several zebrafish ‘Fin’ melanoma systems that are driven by genes such as CRKL, GAB2 and NF1, analogous to human melanomas that lack BRAF/KIT/NRAS alterations." (PMID 39627834, 2024). "Case 61 had an NRASG12C mutation in the invasive portion and a metastasis, whereas the melanoma in situ instead had separate amplifications involving KIT and CRKL, both being known driver mutations of acral melanoma." (PMID 39034322, 2024). "In the cBioPortal database, we found a frequency of 0.5–1.2% samples with CRKL and MAPK1 co-amplification with a trend to mutual exclusivity with KRAS, NRAS and BRAF mutations in NSCLC and melanoma." (PMID 37443114, 2023). "LZTR1 is co-amplified with CRKL and downregulation of each gene inhibits melanoma cell proliferation, albeit to varying degrees." (PMID 35197475, 2022). "Treatment of acral melanoma cell lines with CRKL shRNA induced growth arrest, but only two of five tested cell lines were highly affected." (PMID 35197475, 2022).
glioblastoma (6 papers, 2014 to 2025). The most malignant astrocytic tumor (WHO grade IV). "In a glioblastoma cell line, both CrkL knockdown and Crk/CrkL double knockdown caused cells to shrink and become rounded." (PMID 33801580, 2021). "CrkL expression was detected in U87 and U251 glioblastoma cell lines, and CrkL was activated by transforming growth factor-beta 1 (TGF-β1)." (PMID 40362257, 2025). "The expression levels of CT10 regulator of kinase (Crk) and Crk-like (CrkL) are elevated in many human cancers, including glioblastoma (GBM), and are believed to contribute to poor prognosis." (PMID 33561443, 2021). "When knockdown of both Crk and CrkL was induced, cell migration was completely blocked, suggesting the unique and overlapping functions of Crk and CrkL in glioblastoma cells." (PMID 33801580, 2021). "Using these siRNAs, single and double knockdowns of Crk and CrkL were induced in a glioblastoma cell line to analyze the resulting cellular phenotypes quantitatively." (PMID 33801580, 2021). "Additionally, the knockdown of CrkL significantly influenced the migration of U87 and U251 glioblastoma cells in response to TGF-β signaling." (PMID 40362257, 2025). "In addition, using siRNAs to achieve CrkL knockdown in the U-118MG human glioblastoma cell line resulted in a notable reduction in cell size, alongside a marked inhibition of cell proliferation and adhesion." (PMID 40362257, 2025). "While CrkL knockdown reduced glioblastoma cell migration, Crk knockdown delayed the cell migration." (PMID 33801580, 2021). "Interestingly, migration and invasion of glioblastoma and colorectal, pancreatic, ovarian, cervical, gastric, and liver cancer cells were dependent upon both Crk and CrkL." (PMID 33801580, 2021). "CRKL knockdown in glioblastoma cell lines significantly reduced wound healing and invasion." (PMID 24913448, 2014). "On the other hand, CrkL knockdown, but not Crk knockdown, inhibited glioblastoma cell invasion, and Crk/CrkL double knockdown completely blocked cell invasion." (PMID 33801580, 2021). "In addition, individual and combined knockdown of Crk and CrkL in U-118MG glioblastoma cells demonstrated that CrkL knockdown and Crk/CrkL double knockdown, but not Crk knockdown, inhibited cell proliferation." (PMID 33801580, 2021). "Also, the double knockdown of Crk and CrkL completely blocked the migration and invasion of U-118MG human glioblastoma cells, an effect that could be mitigated by the transient overexpression of CrkL, but not Crk." (PMID 40362257, 2025).
lung adenocarcinoma (6 papers, 2016 to 2025). A carcinoma that arises from the lung and is characterized by the presence of malignant glandular epithelial cells. "For instance, CRKL was identified as a transcriptional target of Hh-GLI2 pathway in lung adenocarcinoma and played an essential role in GLI2-driven cell proliferation and migration." (PMID 40045194, 2025). "CRKL overexpression was also discovered to promote cell proliferation, migration and invasion in lung adenocarcinoma." (PMID 38289488, 2024). "Additionally, elevated CCL19 was a good prognostic factor in lung adenocarcinoma patients, suggesting that CCR7/CrkL interactions are variable and might be tumor type specific." (PMID 35203305, 2022). "In a study aimed at investigating the interactions between CrkL and non-receptor kinase, c-ABL and CCR7 in surgically resected lung adenocarcinoma from 120 patients, high CCR7 mRNA expression paralleled expressions of CrkL and c-ABL and was indicative of a better prognosis." (PMID 35203305, 2022).
colon cancer (5 papers, 2020 to 2024). "While CrkL knockout blocked SASH1 deficiency-induced EMT in HCT116 colon cancer cells, Crk/CrkL double knockout inhibited Src activation-induced EMT." (PMID 33801580, 2021). "Loss of both Crk and CrkL by CRISPR/Cas9 caused inhibition of proliferation of colon cancer cells." (PMID 33801580, 2021). "Reported as an adaptor protein for RAS/MAPK, JAK/STAT, and PI3K pathways, CRKL led to the overexpression of apoptosis-inhibited gene BCL-2 in colon cancer." (PMID 33094104, 2020).
ovarian carcinoma (5 papers, 2018 to 2024). A malignant neoplasm originating from the surface ovarian epithelium. "This investigation showcased a comprehensive genome-wide methylation profile of epithelial ovarian cancer (EOC) and identified six hypermethylated/downregulated genes, (POLR3B, PLXND1, GIGYF2, CRKL, STK4, and BMP2) as potential diagnostic targets." (PMID 38627856, 2024). "While lung, breast, and ovarian cancer have been reported to have CrkL overexpression, ovarian and head and neck cancer have been reported to be dependent on CrkL for tumor cell migration and invasion." (PMID 33801580, 2021). "Published proteomics and molecular biology studies suggest up-regulation of ACTN4, CRKL, GELS, HSPA8, talin-1, tubulins and WDR1 in ovarian cancer." (PMID 29344361, 2018). "Furthermore, CrkL knockdown led to inhibition of TGF-β1-induced cell motility in glioma and ovarian cancer cells." (PMID 33801580, 2021). "Interestingly we observed Non-CpG site methylation in the case of POLR3B and CRKL which was statistically significant in discriminating ovarian cancer samples from normal controls." (PMID 38627856, 2024). "Our results indicate CRKL as a hypermethylated gene but on validation through targeted sequencing, one hypomethylated non-CpG site (CpT-21,268,802 (p-value = 0.0130) turned out to be very significant in discriminating ovarian cancer from non-cancerous state." (PMID 38627856, 2024).
rhabdomyosarcoma (5 papers, 2021 to 2025). A rare aggressive malignant mesenchymal neoplasm arising from skeletal muscle. "CrkL exhibited consistent and elevated expression levels in both rhabdomyosarcoma cell lines and tumor tissues." (PMID 40362257, 2025). "The presence of CrkL was essential for the proliferation of both alveolar and embryonal subtypes of rhabdomyosarcoma." (PMID 40362257, 2025). "The expression level of the CrkL protein is markedly high in cell lines, xenografts, and human tumor samples in both alveolar and embryonal subtypes of rhabdomyosarcoma." (PMID 38338729, 2024). "In sarcoma Rh30 cells, the reduction in CrkL protein expression resulted in a decrease in the phosphorylation and activation of YES1, subsequently causing cell cycle arrest of rhabdomyosarcoma cells and delayed xenograft growth." (PMID 38338729, 2024). "The overexpression of the adaptor protein Crk-like (CrkL) enhances the growth and progression of rhabdomyosarcoma." (PMID 38338729, 2024).
acral melanoma (4 papers, 2022 to 2024). "Importantly, our study demonstrates that LZTR1 and CRKL—two of the top genes associated with 22q11.21 amplification in acral melanoma—facilitate anchorage-independent growth in normal human melanocytes, likely by reducing E-cadherin, increasing N-cadherin, and activating integrin β1." (PMID 35197475, 2022). "Recently, CRK‐Like (CRKL) was found to be amplified in acral melanoma, where its protein product is bound to DOCK1 and DOCK5." (PMID 36271211, 2023).
bladder cancer (4 papers, 2019 to 2024). "In bladder carcinoma cell lines, CRKL is hyperphosphorylated at S107; however, the function of this phosphorylation is unclear." (PMID 31108958, 2019). "However, CRKL is overexpressed in bladder cancer and inhibits tumor cell proliferation and migration." (PMID 37894400, 2023). "CRKL is another adaptor protein that is overexpressed in many cancers, including bladder carcinoma." (PMID 31108958, 2019).
angiosarcoma (3 papers, 2015 to 2025). A malignant tumor arising from the endothelial cells of the blood vessels. "RAS had more frequent MYC, FLT4, CRKL, HRAS, and KMT2D alterations than sporadic angiosarcomas." (PMID 38256700, 2024).
endometrial carcinoma (3 papers, 2019 to 2025). A malignant tumor arising from the epithelium that lines the cavity of the uterine body. "The transfection of human endometrial carcinoma Ishikawa cells with a plasmid encoding CrkL resulted in an increased capacity for colony formation among the transfected cells." (PMID 40362257, 2025). "The overexpression of CrkL, achieved through the transfection of a plasmid into Ishikawa cells derived from human endometrial carcinoma, significantly stimulated cell proliferation and advanced cell cycle progression." (PMID 40362257, 2025). "In contrast, cell cycle progression was observed with CrkL overexpression in NSCLC and Ishikawa endometrial carcinoma cell lines." (PMID 33801580, 2021).
head and neck cancer (3 papers, 2019 to 2024). A primary or metastatic malignant neoplasm affecting the head and neck. "While immunohistochemical staining cannot differentiate between the membrane-bound fraction of CrkL and the intracellular protein, it is in accordance with the data published by others confirming high levels of CrkL in tissues from numerous tumors, such as lung, gastric, and head and neck cancers." (PMID 31323992, 2019).
head and neck squamous cell carcinoma (3 papers, 2021 to 2025). A squamous cell carcinoma that arises from any of the following anatomic sites: lip and oral cavity, nasal cavity, paranasal sinuses, pharynx, larynx, and salivary glands. "CrkL knockdown in head and neck squamous cell carcinoma cells, HSC-3 and HSC-4, resulted in a notable reduction in cell motility." (PMID 40362257, 2025). "Analogously, it has been found that CRKL regulated neutrophil adhesion, brain neuron development, T cell receptor signaling, as well as tumorigenesis of head and neck squamous cell carcinoma via binding to C3G and activating the Rap1 pathway." (PMID 40045194, 2025). "The proliferation of head and neck squamous cell carcinoma cells, HSC-3 and HSC-4, significantly decreased in the presence of CrkL knockdown relative to the control group." (PMID 40362257, 2025).
liver cancer (3 papers, 2020 to 2024). An epithelial or non-epithelial malignant neoplasm that arises from the liver. "miR-124-3p-CRKL axial function could be of great importance in the fundamental research, clinical diagnosis, and treatment of liver cancer." (PMID 33094104, 2020).